IL6 (interleukin 6)
Diseases named in the same sentence as IL6 in open-access papers (continued):
Sharing a sentence is not in itself a finding about the gene and the disease.
Obesity (continued). "Therefore, understanding how IL-6 trans-signaling elicits a cellular pro-arrhythmic phenotype and its use as an anti-arrhythmic target in a model of obesity remain unmet clinical needs." (PMID 39125976, 2024). "Therefore, the assessment of the effect of the presence of IL6 and INS polymorphisms in patients with obesity or T2D seems to be an interesting and justified endeavour." (PMID 38250713, 2024). "In addition, adipocytes of individuals with obesity secrete inflammatory cytokines, such as tumor necrosis factor α (TNFα) and interleukin-6 (IL-6), which induce an inflammatory state." (PMID 38327997, 2024). "During obesity, serum levels of IL-6 as well as Il6 gene expression are augmented in AT." (PMID 38482013, 2024). "Comparable to the effects of light-intensity walking on the release of IL-6, our research indicated significant and positive changes during the intervention phase regarding lipid metabolism in normoglycemic young adults with overweight and obesity." (PMID 39199416, 2024). "As with TNFα, the plasma level of IL-6 increases with obesity and insulin resistance." (PMID 38257186, 2024). "Furthermore, the data obtained for IL-6 were significantly higher in zebrafish from obesity groups 1 and 2, being even higher in females and males from obesity group 2 (overfed with Artemia sp)." (PMID 39408365, 2024). "Molecular markers of obesity (e.g., IL-6, CRP, IL-1 β) increase the generation of MDSCs." (PMID 39399429, 2024). "Furthermore, among the pro-inflammatory cytokines, IL-6 emerged as one of the potential mediators that links obesity-derived chronic inflammation to insulin resistance." (PMID 38257186, 2024). "First, obesity may lead to elevated levels of inflammatory cytokines such as tumor necrosis factor-α, interleukin-6, and C-reactive protein." (PMID 38577567, 2024). "It is also noted that obesity in non-asthmatic adolescents is associated with increased sputum mRNA expression of IL6, IL8, IL13, IL17, IL23, and IFN-γ." (PMID 38629073, 2024). "On the other hand, methylated CpGs within the ADORA2B locus were shown to mediate an association between BMI and blood pressure, while some other SNPs in ADORA2B highly correlate with inflammatory biomarkers IL‐6 and C‐reactive protein and other obesity‐related traits." (PMID 39578713, 2024). "Conditions such as obesity, type 2 diabetes, and metabolic syndrome frequently coexist with a chronic inflammatory state marked by elevated production of inflammatory adipokines, including interleukin-6 (IL-6) and tumor necrosis factor-alpha (TNF-α)." (PMID 38793119, 2024). "Obesity is a low-grade inflammation that is presented by elevated concentrations of circulating cytokines such as C-reactive protein, tumor necrosis factor-α) and interleukins such as IL-6." (PMID 38243194, 2024). "Furthermore, the observed significant reductions with comparatively large effect sizes in PBMC gene expressions of IL-6, IL-1β, and leptin suggest the potential for controlled inflammation in obesity after NS oil supplementation." (PMID 38178093, 2024). "Obese epicardial adipose tissue, a rich local source of IL-6, may predispose to increased VT/SCD risk, highlighting its utility as an anti-arrhythmic target in a model of obesity VT." (PMID 39063055, 2024). "Elevated levels of pro-inflammatory cytokines, such as TNF-α and IL-6, occur concomitantly with an increase in lipid content in white adipose tissue (WAT), contributing to the development of complications associated with obesity." (PMID 38542720, 2024). "This difference was noted only in the morbid obesity group and can be attributed to the fact that these patients have a greater degree of inflammation, as indicated by the higher concentrations of IL-6 in our study, especially in children who are relatively free of the complications of obesity." (PMID 39339733, 2024).
Obesity (continued). "The study details how increases in adipose tissue due to obesity lead to heightened inflammation and macrophage infiltration, producing pro-inflammatory cytokines such as tumor necrosis factor-alpha and interleukin-6 (IL-6)." (PMID 39280570, 2024). "Additionally, IL-6 supports alternative macrophage activation, which is protective against obesity-induced tissue inflammation and insulin resistance." (PMID 39337980, 2024). "Obesity primarily contributes to chronic low-grade inflammation by releasing a surge of signaling molecules, including the adipokines leptin and resistin, the cytokine interleukin-6 (IL-6), and the chemokine monocyte chemoattractant protein-1 (MCP-1)." (PMID 39717478, 2024). "Moreover, obesity changes the baseline levels of serum cytokines/adipocytokines IL-6, TNF-α, and CRP/hs-CRP." (PMID 39564133, 2024). "Moreover, obesity is known to induce systemic inflammation through greater secretion of pro-inflammatory cytokines like tumour necrosis factor-alpha and interleukin-6." (PMID 38421551, 2024). "SphK1 affects the migration and activation of inflammatory cells like macrophages and lymphocytes, as well as the production of cytokines including tumor necrosis factor-alpha (TNF-α), interleukin-6 (IL-6), and IL-10, thus serving both pro-inflammatory and anti-inflammatory functions in obesity." (PMID 39777222, 2024). "Positive associations of increased IL-6 levels with obesity in relation to levels in the case of normal body weight suggest a correlation with the ongoing inflammation in obese people, increasing the risk of developing various diseases in the future." (PMID 38786737, 2024). "In addition to CRP, increased nitric oxide, tumor necrosis factor alpha (TNF-α), and IL-6 have been reported in women with overweight/obesity." (PMID 39236809, 2024). "If overweight/obesity induces elevated CSF IL‐6 levels, this elevation may affect the brain and potentially increase the risk of neuropsychiatric disorders." (PMID 39401137, 2024). "Therefore, although the exact association of nap duration with IL-6 as well as CRP is unclear, excessive napping probably leads to increased levels of IL-6 and CRP, increasing the risk of obesity and subsequent T2DM." (PMID 38590820, 2024). "Thus, the decrease in NA concentration explains the increase in the IL-1β and the absence of significant modifications in the concentration of IL-6 in the present model of obesity." (PMID 39064652, 2024). "These elevated CNS leptin levels may subsequently induce IL‐6 production in CNS, resulting in increased CSF IL‐6 levels secondary to overweight/obesity." (PMID 39401137, 2024). "Treatment that reduces obesity symptoms could reduce epidermal thickness and eosinophil/mast cell infiltration, along with a reduction in IgE, IL-4, IL-6, TNF-α, and AD-like lesions." (PMID 39564133, 2024). "Therefore, to contribute to the ongoing discussion regarding the genetic predictors of obesity and the inconsistencies observed in different populations, we decided to evaluate IL-6 rs1800795." (PMID 39769263, 2024). "Interestingly, we found that QT prolongation due to overactivated IL-6 trans-signaling can be prevented with olamkicept, highlighting an emerging and important anti-arrhythmic role for olamkicept in obesity arrhythmias." (PMID 39063055, 2024). "Moreover, others have shown that RvD1 and RvD2 decreased TNFα and IL-6 and increased adiponectin in cultured adipocytes and adipose tissue explants using a mouse model of diet-induced obesity." (PMID 39337391, 2024). "According to a study, obesity was linked to precancerous alterations in the transcriptome, while an elevated body mass index was linked to an increase in two proinflammatory colonic cytokines, TNF- α and IL6." (PMID 39273314, 2024). "They found that obesity, IGT, and T2DM were associated with increased IL-6 and CRP levels." (PMID 39408723, 2024).
Obesity (continued). "IL-6 is known to be activated in the context of obesity, and most likely, the SARS-CoV-2 virus could amplify the primed cytokine response in AT." (PMID 38474155, 2024). "Therefore, not only does the infection promote inflammatory microenvironment – fatty acid synthesis in vitro model – but also obesity and metabolic dysfunctions act on IL-6 elevation." (PMID 38533504, 2024). "Clinically, the elevated systemic levels of IL-6 and TNF-α are particularly concerning, since these pro-inflammatory molecules are directly associated with insulin resistance and hyperinsulinemia, which are common in individuals with obesity." (PMID 39125408, 2024). "This may be because the entire Mexican population had a high BMI; in exchange, the DG+C group had a significantly higher BMI than the control group in the current study, indicating that increasing IL-6 may be related to obesity." (PMID 39519313, 2024). "Obesity manifests with heightened inflammation levels characterized by immune cell infiltration, notably macrophage infiltration, and the increased secretion of pro-inflammatory cytokines such as IL-1β and IL-6 within adipose tissue." (PMID 38672517, 2024). "This suggests that IL6′s role in endometrial cancer pathophysiology is likely modulated by obesity." (PMID 38339282, 2024). "Central IL-6Rα activation and IL-6 action is enhanced in obesity." (PMID 38474057, 2024). "Conversely, obesity is linked to surged dose of interleukin 6, who presents a negative impact on synaptic plasticity and neurogenesis." (PMID 38520024, 2024). "Bibliometric analysis revealed that in 2004–2013 research on obesity and its complications (such as metabolic syndrome, T2D) focused on analysis of skeletal muscle, fibronectins, IL-6, and adipokines, as well as molecular processes related to insulin resistance and inflammation." (PMID 39376657, 2024). "Second, they suggest that targeting exercise‐induced cytokines, such as IL‐6 and irisin, may be a promising therapeutic approach for obesity." (PMID 39221051, 2024). "The integrative metabolic function of myokines and adipokines has recently been emphasized by the demonstration that interleukin 6 (IL-6), derived from either muscle or adipose tissue in the context of obesity, facilitates communication between intestinal cells and pancreatic islets." (PMID 39596226, 2024). "Additionally, mechanisms such as oxidative stress, inflammation (release of cytokines, such as TNF-α and IL-6), and apoptosis induced by aging and obesity impair testosterone synthesis, spermatogenesis, and sperm quality." (PMID 39765826, 2024). "Therefore, it appears that IL-6 signaling predominantly contributes to the beneficial effects of endurance training on the improvement of obesity and related metabolic outcomes." (PMID 38321233, 2024). "Because IL-18 has increased expression in obesity and HF and contributes to heart rhythm disorders and VT in mice, we suspect that IL-18 may heighten the IL-6 effects on ion channel function, pro-arrhythmic AP phenotypes, and ventricular arrhythmia risks." (PMID 39125976, 2024). "Additionally, adipose tissue dysfunction in obesity leads to the release of proinflammatory cytokines such as IL-6 and TNF-α that can directly interfere with insulin signaling within cells, further exacerbating insulin resistance (Fève and Bastard, 2009)." (PMID 39717478, 2024). "The reduction in the mRNA levels of pro-inflammatory cytokines (TNF-α, IL-6, and IL-1β) signifies a robust anti-inflammatory effect of CME, offering a potential mechanism for its protective role against hepatic inflammation associated with obesity." (PMID 38999918, 2024). "Increasing numbers of M1 macrophages as well as activated adipocytes present in inflamed fat tissue produce TNF-α, IL-6 and other inflammatory mediators including leptin and resistin that promote the occurrence of cardio-metabolic syndrome and hypertension in obesity." (PMID 38541059, 2024).
Obesity (continued). "Prolonged obesity and HFD intake are well associated with elevated IL-6 trans-signaling." (PMID 39769189, 2024). "It was found that CRP and IL-6 increased with obesity-related traits." (PMID 39337223, 2024). "Based on our results, IL-6 can be assessed as a marker in managing obesity." (PMID 38786737, 2024). "Moreover, ERK pathway overactivation in skeletal muscle can lead to inflammation through activation of TNF-α, IL-6, IL-1ß, and contribute to metabolic disorders such as type 2 diabetes and obesity." (PMID 38451972, 2024). "Obesity also enhances the expansion of an IL-6-positive natural killer (NK) cell subpopulation." (PMID 38474057, 2024). "To determine how obesity affects neuroinflammation in female mice, we examined the mRNA expression levels of proinflammatory cytokines (TNFα, IL1β, and IL6) and markers of microgliosis (Iba1) and astrogliosis (GFAP) in three distinct brain subregions (hypothalamus, hippocampus, and cerebral cortex)." (PMID 39230054, 2024). "Inflammatory markers measured in obesity-related studies often include IL-6, TNF-α, and CRP." (PMID 38792936, 2024). "Moreover, the results indicated that high fat consumption (SFAs) increased IL-6 and leptin levels in participants with obesity." (PMID 39700087, 2024). "Adipokines such as leptin and proinflammatory cytokines such as TNFα, IL-6 and IL-18 are involved in the pathogenesis of obesity-related insulin resistance in women with PCOS but seem also to be directly implicated in the pathogenesis of ovarian and adrenal dysfunction." (PMID 38540265, 2024). "For example, obesity, inflammaging, cardiovascular disease, hypertension, and rheumatoid arthritis are characterized by elevated concentrations of circulating cytokines, such as IL-1b, IL-6, IL-8, IL-10, IL-13, TNF-α, and IFN-γ." (PMID 39408907, 2024). "In individuals with obesity, the levels of inflammatory adipokines such as leptin, adiponectin, interleukin-6 (IL-6), heparin-binding epidermal growth factor-like growth factor (HB-EGF), and vascular endothelial growth factor (VEGF), which are secreted by adipose tissue, are elevated." (PMID 39524226, 2024). "Our study shows that IL-6 may be an important cytokine and marker of inflammation in people with obesity, because its concentration is significantly increased in the case of obesity." (PMID 39769504, 2024). "Consequently, IL-6 serves as a critical inflammatory mediator in obesity, with its secretion influenced by a range of physiological or pathological factors, including hormones, cytokines, diet, physical activity, stress, and hypoxia." (PMID 39201638, 2024). "In addition, chronic systemic inflammation is recognized as part of insulin resistance syndrome, T2DM, and obesity and is characterized by increased IL-6 and CRP levels, as well as decreased levels of adiponectin (ADIPOQ) and IL-10." (PMID 39408723, 2024). "In addition, overweightness and obesity in children have been associated with elevated IL-6, CRP, and MCP-1, and CRP has been positively correlated with MCP-1, IL-6, and IL-10." (PMID 38396489, 2024). "Obesity group 2 was interesting to investigate in terms of weight gain [167 mg; p < 0.0001), changes in fasting glucose [48.33 (4.14) mg/dL; p = 0.003), and inflammatory parameters [IL-6: 4.24 (0.18) pg/mL; p = 0.0015]." (PMID 39408365, 2024). "A decreased abundance of Firmicutes, a decreased Firmicutes to Bacteroidetes ratio (F/B), and a lower expression of IL-6 concentration after overexpression of hepatic miRNA-29a (anti-inflammatory) may be relevant to obesity and MASLD in C57BL/6 mice." (PMID 39684547, 2024). "IL-6 produced during exercise may alter leptin in the ARC, affecting post-exercise eating behavior IL-18 knockdown mice cause hyperphagia, obesity, and insulin resistance." (PMID 39691381, 2024). "In subjects with overweight and obesity, circulating levels of IL-6 are found to be augmented." (PMID 38482013, 2024).
Obesity (continued). "Although a direct metabolite mediating these effects was not identified, it is important to recall IL6 involvement in obesity-associated inflammation and recent findings where IL6 signaling was reported to render resistance to ICB therapy." (PMID 39253073, 2024). "For obesity, adipose tissues can release proinflammatory cytokines (e.g., tumor necrosis factor alpha, interleukin-1, interleukin-6, and adiponectin), which could activate the nitric oxide pathway in the brain and then cause headaches." (PMID 38378448, 2024). "Moreover, observations suggest that a marked elevation of IL-6 holds an intricate link to excess body fat, body mass index (BMI), and obesity in patients with HFpEF, further agreeing with the proinflammatory consequences of lipotoxicity." (PMID 39769189, 2024). "Obesity is currently acknowledged as an independent risk factor for the onset of Intervertebral Disc Disease (IVDD) and is significantly correlated with elevated levels of IL-6 and systemic pro-inflammatory cascades." (PMID 39697339, 2024). "Moreover, these three bacterial strains were significantly associated with certain adipo-myokines related to obesity or inflammation (LIF, FSTL1, FGF21, SPARC, and IL6)." (PMID 39391493, 2024). "In addition, IL-6 is highly expressed in adult adipose tissue and is positively correlated with obesity." (PMID 39065704, 2024). "Obesity is associated with chronic inflammation, characterized by the infiltration of immune cells that release pro-inflammatory cytokines such as Tumor Necrosis Factor-α (TNF-α) and Interleukin-6 (IL-6)." (PMID 39741884, 2024). "In obesity, due to increased body mass, the adipose tissue is dysfunctional, with an altered expression of cytokines and adipokines; as a result, pro-inflammatory plasma levels of cytokines such as interleukin-6 and tumor necrosis factor alpha increase in obesity patients." (PMID 39596974, 2024). "Obesity and asthma have been linked through chronic systemic inflammation driven by adipokines such as leptin, adiponectin, TNF-α, monocyte chemotactic protein-1 (MCP-1), and IL-6." (PMID 40474934, 2024). "However, as noted in a recent review of studies investigating hepcidin and IL-6 levels in children with obesity, this has only rarely been done." (PMID 38599666, 2024). "Chronic hyperleptinemia due to obesity and elevated levels of inflammatory cytokines like interleukin-6 (IL-6) and tumor necrosis factor-alpha (TNF-α) are hypothesized to lower the CSD threshold, making the brain more susceptible to migraine triggers." (PMID 39456943, 2024). "Additionally, VAT can also induce obesity-related subclinical inflammatory changes, such as increased production of interleukin-6, tumour necrosis factor-α, and C-reactive protein, which can precede the pathogenesis of CKD." (PMID 39698033, 2024). "Moreover, the same obesity pathways that connect IL-6 trans-signaling to ventricular arrhythmias are likely involved in the adverse remodeling associated with other pathologies, including myocardial infarction and HF." (PMID 39125976, 2024). "Furthermore, it explores the role of pro-inflammatory cytokines, such as IL-6 and IL-17a and mother’s obesity as potentially environmental factors of ASD." (PMID 38398873, 2024). "The relationship between obesity and ORG is facilitated by a network of various inflammation-associated cells (e.g., synaptophysin) and a series of inflammatory mediators (e.g., TNF-α and IL-6)." (PMID 39234117, 2024). "Obesity is related to chronic inflammation and inflammatory makers such as IL-6 and tumor necrosis factor-α (TNF-α), which may induce an overreaction of the inflammatory process in response to infection." (PMID 38668323, 2024). "However, in the context of chronic systemic inflammation, as seen in obesity, IL-6 predominantly engages in trans-signaling via its soluble receptor (sIL-6R), promoting catabolic and inflammatory effects in joint tissues." (PMID 39683624, 2024).